ENSG00000274322 (novel protein)
Gene: Protein-coding gene on chromosome 20 (1,317,571 to 1,393,096, reverse strand). Ensembl gene ENSG00000274322.
Genetic constraint (gnomAD): Missense variants: 85 observed, 74.06 expected, observed/expected ratio (o/e) 1.15, 90% interval 0.96 to 1.38. Synonymous variants: 42 observed, 27.13 expected, observed/expected ratio (o/e) 1.55, 90% interval 1.2 to 1.9.